CRP (C-reactive protein)
Diseases named in the same sentence as CRP in open-access papers (continued):
Sharing a sentence is not in itself a finding about the gene and the disease.
colorectal tumor (8 papers, 2009 to 2023). "Pre-treatment levels of IL-6, TNF-α, and CRP were significantly associated with increased phenotypic frailty in colorectal tumors." (PMID 37213604, 2023). "Although numerous studies have greatly improved the knowledge of colorectal tumor genesis, the association between parameters of chronic inflammation such as IL-6, C reactive protein (CRP) and MMP-9 is not fully understood as well as their relation to the progression of CRC." (PMID 30154846, 2018). "Previous studies evaluating the effect of PN enriched with ω3 LE on the immune response of patients with gastric or colorectal tumors found significant differences between groups in reducing the inflammatory response, measured by parameters like IL-6, CRP, and TNF-α." (PMID 38201870, 2023). "In this prospective cohort study, a plasma level of C-reactive protein (CRP) ≥ 10 mg/L was a predictor of inferior three-year overall survival after oncologic surgery in older cancer patients, and also for the specific group of older patients with a colorectal tumor." (PMID 33920422, 2021).
cutaneous vasculitis (8 papers, 2014 to 2025). Inflammation of the blood vessel wall characterized by palpable purpura. "Other factors such as older age, male gender, dysphagia, skin necrosis, cutaneous vasculitis, rapid onset of the disease, elevated creatinine kinase, and elevated C-reactive protein are closely associated with the risk of malignancy." (PMID 40535138, 2025). "An extensive meta-analysis of clinical trials found older age, male sex, dysphagia, cutaneous necrosis, cutaneous vasculitis, rapid onset (<4 weeks), elevated CK, higher ESR, and higher CRP as factors to be associated with higher risk." (PMID 27561848, 2016). "Plasma sPD-L1 levels were positively correlated with plasma C-reactive protein (CRP) in both systemic and cutaneous vasculitis." (PMID 34625602, 2021). "He went on to suffer failure to thrive, developmental delay, livedo reticularis, and vesicular rash, but without cutaneous vasculitis, and with normal C-reactive protein and erythrocyte sedimentation rates." (PMID 30038614, 2018). "For PM/DM patients, the following factors are all associated with an increased risk of malignancy: older age, age greater than 45, male sex, dysphagia, cutaneous necrosis, cutaneous vasculitis, rapid onset of myostis (<4 weeks), elevated CK, higher ESR, higher CRP levels." (PMID 24713868, 2014).
gastric adenocarcinoma (8 papers, 2012 to 2025). "A prospective, non-randomized study comparing RCS (n = 30) and LCS surgery (n = 120) for early gastric adenocarcinoma reported a lower postoperative CRP and interleukin-6 response in the LCS group." (PMID 34022914, 2021). "However, this study presented a composite score of prealbumin and CRP suggesting that it may be a strong prognostic score in patients with inoperable gastric adenocarcinoma." (PMID 26904109, 2016). "Six candidate proteins (OPN, sVCAM1, SAA, CRP, AGP and GRO) were measured in serum samples from 219 newly-diagnosed patients with gastric adenocarcinoma and 333 healthy control subjects using Luminex multiplex assays." (PMID 25884401, 2015). "Second, except for DD and C-reactive protein, the levels of all algorithm-selected biomarkers were significantly lower in patients with gastric adenocarcinoma than in the controls (data not shown)." (PMID 22240791, 2012). "Given the observed downregulation of miR-129 in gastric adenocarcinoma and its inverse correlation with systemic inflammatory and metabolic markers (CEA, CA 19-9, LDH, and CRP), we further explored whether these alterations extend beyond tumor biology to affect vascular and neurological function." (PMID 41157276, 2025).
kidney injury (8 papers, 2017 to 2026). Trauma to the kidney. "The study assesses the tissue-specific effect of HO-1 on CRP expression and shows a more prominent effect in the kidney, supporting the important role of HO-1 in mediating immune-mediated kidney injury." (PMID 36670923, 2022). "But bafilomycin A1, autophagy suppressor exerts opposite action and worsened IRI-induced kidney injury in CRP overexpression mice." (PMID 28886014, 2017). "Added to this, C-reactive protein (CRP, a sensitive biomarker of inflammation) has been shown to increase among sugarcane workers performing the physically most demanding tasks during the harvest season, especially in those developing kidney injury." (PMID 39369140, 2025).
latent infection (8 papers, 2014 to 2023). "In our case, good control of the primary tumor achieved with chemotherapy and the past history of wound infection led us to suspect latent infection as the cause of increased CRP, thus delaying detection of lymph node metastases." (PMID 37794336, 2023).
Legionella (8 papers, 2009 to 2025). "Blood test findings for an early presumptive diagnosis of Legionella pneumonia were decreased serum sodium and platelets, increased CRP, and increased serum LDH levels." (PMID 34409491, 2021). "However, in our study, Legionella pneumonia leukocytes and CRP were significantly elevated with mean ± SD of (11.36 ± 4.93) × 109/L and 159.36 ± 100.66 mg/." (PMID 40630483, 2025). "In the end, clinical and laboratory factors previously found to be predictive of Legionella pneumonia either were not significantly different in the two groups or they were not tested consistently (e.g., C-reactive protein, lactase dehydrogenase, Creatine phosphokinase (CPK)." (PMID 31952117, 2020).
leprosy (8 papers, 2017 to 2023). Leprosy is a chronic infectious disease affecting primarily the skin and peripheral nervous system. "And, another study found that CRP was associated with Mycobacterium leprae in skin lesions, but again, other data indicate that there is a wide range for CRP concentrations in leprosy individuals." (PMID 37873776, 2023). "Identifying a host biomarker signature to support diagnosis has made a significant advance, with high titters of anti-PGL-1 IgM, IP-10/CXCL-10 and CRP being associated with leprosy." (PMID 35416839, 2022). "High αPGL-I IgM, IP-10, and CRP levels, relative to controls, were associated with MB leprosy, whereas ApoA1 and S100A12 levels were critical for identification of both patients groups." (PMID 33490914, 2021). "Comparison of means between tuberculoid and lepromatous leprosy revealed a statistically higher C-reactive protein value in lepromatous leprosy (p=0.014)." (PMID 35449687, 2022). "This showed that the earlier observed pattern for patients with MB leprosy of high αPGL-I IgM, CRP, and IP-10 R values was confirmed in both the Bangladeshi and South Korean cohorts." (PMID 33490914, 2021). "Higher levels of CCL4WCS were also observed in the households where HCs of the primary index case were diagnosed with leprosy upon first physical investigation at intake (p = 0.0002) as well as increased levels of CRP (p = 0.025)." (PMID 32849645, 2020). "Levels of anti-PGL-I IgM antibody (humoral immunity), IP-10, CCL4 and CRP (cellular immunity) were measured in blood collected from leprosy patients, household contacts and healthy controls from each area." (PMID 30560920, 2018). "In our study, most leprosy patients with plantar ulcers had normal serum levels of albumin and transferrin, but high serum CRP levels, which indicate the existence of an inflammatory process." (PMID 28866982, 2017). "Normal serum levels of CRP were detected in 92.9% of patients with PB leprosy and 68.9% of patients with MB leprosy." (PMID 28866982, 2017). "High levels of CRP were detected in 51.6% of leprosy patients with plantar ulcers and only 9.1% of patients without plantar ulcers (P < 0.001)." (PMID 28866982, 2017). "Our results show significantly higher CRP levels in leprosy patients with plantar ulcers (P < 0.0001), most of whom had MB leprosy." (PMID 28866982, 2017). "Most leprosy patients with plantar ulcers have normal levels of serum albumin and transferrin and high CRP levels, which indicates the presence of an inflammatory process." (PMID 28866982, 2017). "Elevated levels of CRP were observed in 7.1% of patients with PB leprosy and 31.1% of patients with MB leprosy." (PMID 28866982, 2017). "They evaluated the levels of anti-PGL-1 IgM antibody as well as IP-10, CCL4 and CRP in blood collected from leprosy patients and observed that combined detection of these biomarkers significantly improved the diagnostic potential, particularly for PB leprosy in all studied regions." (PMID 35416839, 2022). "Non-invasive inflammatory biomarkers, such as C- reactive protein, erythrocyte sedimentation rate, leukocyte count, procalcitonin, interferon alpha, and tumor necrosis factor α (TNF-α) have been widely used to improve diagnostic accuracy of leprosy reactions." (PMID 32083213, 2020). "Elevated levels of CRP in LL/BL (MB) leprosy were in agreement with other reported studies." (PMID 30560920, 2018). "Recently, a multi-biomarker test (MBT) evaluating αPGL-I IgM, IP-10, CRP, S100A12, and ApoA1 was successfully used to discriminate patients with MB and PB leprosy from control individuals in high and low leprosy endemic areas." (PMID 35416839, 2022). "A host biomarker signature of αPGL-I IgM, IP-10, CRP, ApoA1, and S100A12 was identified, covering both the humoral and cellular pole of the immunopathologic leprosy spectrum." (PMID 33490914, 2021).
leprosy (continued). "Overall, the data show that IP-10 was the most significant cellular marker to identify both LL/BL and BT/TT leprosy patients in low- and high endemic populations, anti-PGL-I IgM and CRP are relevant for diagnosis of LL/BL patients and CCL4 contributes to the detection of BT/TT patients." (PMID 30560920, 2018).
lymphadenitis (8 papers, 2021 to 2025). Acute or chronic inflammation of one or more lymph nodes. "In patients with TB lymphadenitis, ferritin levels were raised in 6/47(13%), CRP in 10/47 (21%), and ADA in 33/47 (70%) of cases." (PMID 39623309, 2024). "When analyzed separately, levels of ferritin (p = 0.046) and CRP (p = 0.017) decreased significantly only at 6 months of treatment, while, ADA levels did not decease at any time point among TB lymphadenitis patients." (PMID 39623309, 2024).
meconium aspiration syndrome (8 papers, 2015 to 2023). A serious condition in which a newborn breathes a mixture of meconium (the first intestinal discharge) and amniotic fluid into the lungs around the time of delivery. "Moreover, trauma, ischemic tissue injury, hemolysis or meconium aspiration syndrome can result in increased CRP concentrations in the first 24–48 h of life." (PMID 33419284, 2020). "CRP levels can be raised by non-infectious illnesses like traumatic or ischemic tissue injury, meconium aspiration syndrome, and hemolysis." (PMID 35449688, 2022).
meningioma (8 papers, 2020 to 2023). A generally slow growing tumor attached to the dura mater. "Therefore, interleukin-6 secretion is inversely correlated with the growth velocity of meningiomas and both serum CRP and plasma fibrinogen are linked to the promotor of the interleukin-6 gene." (PMID 35205781, 2022). "Plasma fibrinogen and serum C-reactive protein are both linked to the interleukin-6 gene promoter, and those parameters may be induced by the autocrine secretion of interleukin-6 by meningioma cells." (PMID 34298854, 2021). "The simple association between quick-to-use biomarkers such as serum CRP and tumor growth in meningiomas might be explained by the capability of human meningioma cells to secrete interleukin-6, which has an autocrine inhibitory role in the regulation of neoplastic cell growth." (PMID 35205781, 2022). "Those pathophysiological pathways enable the secretion of CRP in hepatocytes by induction of IL-6 secreted by meningiomas." (PMID 34829359, 2021). "CRP is capable to polarize human macrophages to an M1 macrophage and simultaneously inhibits the transformation to the M2 phenotype which were found to be pro-tumor macrophages enhancing tumor growth and recurrence in meningiomas." (PMID 34829359, 2021). "Between 2009 and 2022, 710 patients with clinical data, tumor-imaging data, inflammatory laboratory (plasma fibrinogen, serum C-reactive protein) data, and neuropathological reports underwent surgery for primary cranial WHO grade 1 and 2 meningioma." (PMID 36077817, 2022). "Between 2013 and 2019, 208 patients with tumor morphology data, MIB-1 index data, and plasma fibrinogen and serum C-reactive protein (CRP) data underwent surgery for intracranial WHO grade I and II meningioma." (PMID 34298854, 2021). "Furthermore, we recently developed a novel scoring sheet using FibrinOgen, C-Reactive protein, Gender, and peritumoral Edema (FORGE score) as a tool to preoperatively estimate the MIB-1 index and the probability of PFS in cranial meningiomas." (PMID 35205781, 2022). "Between 2000 and 2020, 128 patients with clinical data, tumor imaging data, inflammatory laboratory (plasma fibrinogen, serum C-reactive protein) data, and neuropathological reports (MIB-1, mitotic count, CD68 staining) underwent surgery for spinal WHO grade 1 and 2 meningioma." (PMID 36091152, 2022).
non-alcoholic steatohepatitis (8 papers, 2016 to 2025). "For instance activation of the NF-κB pathway leads to increased transcription of the CRP gene causing the release of CRP from human hepatocytes, perpetuating injury and oxidative stress, furthering the progression of NAFLD to non-alcoholic steatohepatitis." (PMID 27727191, 2016). "Conversely, in a 24-week open-label, uncontrolled pilot study (5 mg/day) in 11 patients with T2DM with non-alcoholic steatohepatitis there were almost no changes in CRP, while in a separate 12-week intervention (10 mg/day) in 36 subjects with T2DM, there was an unexpected increase in median CRP." (PMID 40149704, 2025).
Peptic ulcer (8 papers, 2019 to 2025). The term peptic ulcer refers to acid peptic injury of the digestive tract, resulting in mucosal break reaching the submucosa. "Elevated preoperative CRP levels in perforated peptic ulcer patients may increase the likelihood of postoperative complications by impairing tissue perfusion." (PMID 41164391, 2025).
polymyositis (8 papers, 2013 to 2026). A rare idiopathic inflammatory myopathy characterized by symmetric proximal muscle weakness and elevated muscle enzymes. "The association between C-reactive protein and high-density lipoprotein - cholesterol among untreated patients with early polymyositis in a linear regression model." (PMID 24587064, 2014). "Correlation between CRP and lipid profiles among untreated patients with early polymyositis." (PMID 24587064, 2014). "Although elevated ESR and CRP could suggest inflammatory myositis, the absence of markedly elevated CK levels and a negative serology (e.g., Jo-1 antibodies) strongly support diabetic myonecrosis rather than inflammatory conditions such as polymyositis or IMNM." (PMID 40963896, 2025).
Portal vein thrombosis (8 papers, 2013 to 2026). Thrombosis of the portal vein and/or its tributaries, which include the splenic vein and the superior and inferior mesenteric veins. "We conducted a univariate Cox regression to assess the impact of factors like transcriptomic signature, performance status, liver transplant, BCLC stage, albumin, CRP, nodule count, and portal vein thrombosis on survival, all showing significant associations." (PMID 39456643, 2024). "In multivariate analysis, we adjusted for collinearity, excluding CRP and creating five models that included either transcriptomic signature, portal vein thrombosis, or nodule number." (PMID 39456643, 2024). "Meanwhile, predictors of resolution of portal vein thrombosis included a history of abdominal infection, C-reactive protein and hemoglobin levels, and intake of thrombolytics." (PMID 36691024, 2023). "Child-Pugh class, tumor size > 5 cm, tumor multiplicity, presence of portal vein thrombosis, α-fetoprotein > 200 ng/mL, CRP > 6.3 mg/L and NLR > 2.3 were identified as independent factors for worse survival of HCC (all p < 0.05)." (PMID 23409924, 2013). "Higher serum levels of circulating lncRNA-ATB could be associated with OS, PFS, TNM stage, tumor size, C-reactive protein (CRP), T stage, and portal vein thrombosis." (PMID 36300115, 2022).
Premature rupture of membranes (8 papers, 2021 to 2026). Premature rupture of membranes (PROM) is a condition which occurs in pregnancy when the amniotic sac ruptures more than an hour before the onset of labor. "In cases of preterm premature rupture of membranes, conventional indicators such as white blood cell (WBC) count and C-reactive protein (CRP) have known limitations, and reliable biomarkers for predicting intrauterine inflammation are limited." (PMID 41945573, 2026). "ANC: antenatal check-up; PPROM: preterm premature rupture of membranes; CRP: C-reactive protein; VD: vaginal delivery; LSCS: lower segment cesarean section; Apgar: appearance, pulse, grimace, activity, and respiration." (PMID 35800788, 2022). "This study aimed to evaluate the prognostic value of C-reactive protein velocity (CRPv) and inflammatory burden index (IBI) as novel systemic inflammatory biomarkers in predicting the latent period in pregnancies complicated by preterm premature rupture of membranes (PPROM)." (PMID 40579562, 2025).
purpura (8 papers, 2017 to 2025). A small blood vessel hemorrhage into the skin and/or mucous membranes. "In this study, the presence of purpura was significantly associated with CRP, IL-5 and high BVAS score, suggesting that cutaneous lesions reflected high disease activity of EGPA." (PMID 32770271, 2021). "In the univariate analysis, presence of purpura was associated with increased CRP and IL-5, and high BVAS score." (PMID 32770271, 2021). "Our findings showed that presence of purpura was associated with increased CRP and IL-5, and high disease activity in EGPA." (PMID 32770271, 2021). "Multivariate linear regression analysis of CRP and IL-5 showed that only CRP was related to the presence of purpura (p = 0.0223, 95% confidence interval 0.022–0.21)." (PMID 32770271, 2021). "The erythrocyte sedimentation rate (ESR) and c-reactive protein (CRP) levels were altered in the test performed 14 days after cisplatin administration (2 days after appearance of the first purpura lesion)." (PMID 29212535, 2017). "Multivariate analysis revealed a robust relationship between purpura and CRP." (PMID 32770271, 2021). "Multivariate analysis showed that CRP was the most related marker to purpura." (PMID 32770271, 2021). "Inflammation-related proteins are found inI-HCA (e.g., tumors are positive for serum amyloid A or C-reactive protein) Histologically,focal or diffuse inflammation is seen in I-HCA, along with sinusoid dilatation, congestion,purpura, and bile duct hyperplasia." (PMID 35111517, 2020). "The IgAV patient closest to HC in the space spanned by the two most important PCs had a mild disease with nonnecrotic purpura and also low levels of inflammatory parameters (CRP, SAA and ESR), which might be the reason for the gene signature similar to controls." (PMID 38610060, 2024).